IL6 (interleukin 6)
Diseases named in the same sentence as IL6 in open-access papers (continued):
Sharing a sentence is not in itself a finding about the gene and the disease.
osteoarthritis (continued). "In the group of our chronic patients prevail osteoarthritis and meniscal tears, which can result in higher levels of TNF- α and IL-6." (PMID 39519568, 2024). "Visfatin, a pro-inflammatory adipokine, plays a role in osteoarthritis pathogenesis by upregulating inflammatory mediators such as TNF-α, IL-6, IL-1β, and various MMPs and ADAMTS enzymes, which are principal agents in cartilage catabolism." (PMID 38800150, 2024). "The high efficacy of β-HIVS in reducing inflammation in osteoarthritis was demonstrated by decreasing the expression of PEG2, NO, iNOS, interleukin (IL)-6, (TNF)-α, and COX-2 in chondrocyte cells." (PMID 36977702, 2023). "Osteoarthritis is known to be promoted by inflammatory cytokines (TNF-α, IL-1, IL-6, IL-17, etc.)that stimulate the secretion of matrix metalloproteinases (MMPs) from synovial fibroblasts." (PMID 37623223, 2023). "In rat cartilage tissue of osteoarthritis, miR-137 is also downregulated, and its over-expression can reduce the inflammatory factors (TNF-α, IL-1β, IL-6) via downregulating the TCF4-AMPK/NF-κB pathway." (PMID 38138985, 2023). "LncRNA GACAT3 governed IL-6/STAT3 pathway and induced proliferation of synoviocytes in osteoarthritis." (PMID 37779916, 2023). "We quantified the levels of biomarkers of cartilage and bone anabolism (CPII and N-MID) and catabolism (CTX-I and CTX-II), as well as of osteoarthritis (HA and COMP) and inflammation (IL-6 and PGE2)." (PMID 38069100, 2023). "Further examination of these genes indicated that they were enriched for known pathways related to osteoarthritis progression including serine/threonine protein kinase signaling, BMP signalling and interleukin-6 signalling." (PMID 35088088, 2022). "A large number of inflammatory mediators including IL-6, TNF-α and IL-1β were detected in osteoarthritis." (PMID 35563622, 2022). "The genesCCL2, IL6, andIL1Bwere found to be the common genes across temporomandibular joint (TMJ) and TMJ + osteoarthritis (TMJ-OA) datasets." (PMID 35707787, 2022). "We next examined the levels of TNF-α, IL-6, IL-10 and vascular endothelial growth factor (VEGF) in the serum samples of experimental animals after induction of osteoarthritis." (PMID 35887046, 2022). "It was found that miR-199a-5p also inhibits visfatin (a pro-inflammatory adipokine)-induced IL-6 and TNF-α production to mitigate the progression of osteoarthritis." (PMID 36561044, 2022). "Meanwhile, as a small molecule that regulates interleukin-6 (IL-6)-induced inflammatory responses, RCGD423 also was loaded into MPDA for osteoarthritis treatment by sustained and controlled drug release, according to Wang’s report." (PMID 36234997, 2022). "The predictive strength comprising TRD2 + IL-6 + IL1β + GGGGCT + AGC provedto be the best (AUC: 0.91, 95%CI: 0.87–0.95) for discriminating osteoarthritis patients from controls." (PMID 34073132, 2021). "Inflammation plays an important role in the pathogenesis of OA, in which the chondrocytes, synovial membrane, and surrounding tissues produce large amounts of inflammatory factors such as IL-1β, IL-6, TNF-α, that accelerate the progression of osteoarthritis." (PMID 34976968, 2021). "SHH autocrine treatment of osteoarthritis MSC stimulates proliferation, chondrogenesis, hypertrophy, and replicative senescence with elevated SASP gene expression including IL1B, IL6, CXCL1, and CXCL8." (PMID 34646822, 2021). "The impact of FA on IL‐1β‐induced osteoarthritis chondrocyte toxicity was determined by prostaglandin E2 (PGE2), nitrite, IL‐6, components of the extracellular matrix, and markers of oxidative stress." (PMID 34078001, 2021). "On the other hand, in a mouse model with osteoarthritis, the animals’ treatment with grapes procyanidins was shown to downregulate VEGF, TNFα, Il6 and RANKL expression, protecting the cartilage integrity." (PMID 32664580, 2020).
osteoarthritis (continued). "In addition to detecting the IL-1β, TNF-α, IL-6, IL-17, IL-8, IL-4, IL-10, and IL-13 cytokines, the kit can also detect additional 28 cytokines, so we can also explore whether other factors are involved in the pathogenesis of osteoarthritis." (PMID 32332638, 2020). "The qRT-PCR results showed that the expression levels of ADIPOQ, IL6, and CXCR1 in the synovium of osteoarthritis were significantly increased (p <0.05)." (PMID 31139654, 2019). "The statistical results showed that the expression levels of ADIPOQ, IL6, and CXCR1 in the synovium of osteoarthritis were significantly increased (p <0.05)." (PMID 31139654, 2019). "In vitro and in vivo studies demonstrated that CJM reduced the IL‐1β‐, IL‐6, IL‐17‐ and TNF‐α‐induced up‐regulation of MMP3, MMP13, ADAMTS4, ADAMTS5 and COX‐2 and blocked osteoarthritis development in a destabilization of the medial meniscus mouse model." (PMID 31148341, 2019). "Our previous studies suggested that cytokines (e.g., IL-1β, IL-6, and TNF-α) expressed in articular chondrocytes during the pathogenesis of osteoarthritis and RA increase HIF-2α expression and protein accumulation under normoxia." (PMID 31098335, 2019). "In our study, genetic analysis also revealed the upregulated expression of IL-1, IL-6, and TNF-α in osteoarthritis cartilage in vivo was suppressed by SA." (PMID 30931327, 2019). "The predicted pathway also correlated the Histone Deacetylase 2 (HDCA2) with IL6 and MMP9 and RELA which was seem to be boost the progression of osteoarthritis by repressing cartilage specific gene." (PMID 29731966, 2018). "The verification result showed that the expression levels of IL6, VEGFA, JUN, IL-1β, and ATF3 were significantly increased in osteoarthritis samples (p < 0.05)." (PMID 30186872, 2018). "The previous experiment suggested the involvement of IL6 in osteoarthritis progression through MMP13, which is further established in current study showing IL6 as upregulated DEG in both virus and σB treated group." (PMID 29731966, 2018). "It has been demonstrated that inflammatory factors, including IL-6 and TNF-alpha, are involved in the pathophysiology of osteoarthritis." (PMID 28373981, 2017). "In the early stage of osteoarthritis, synovium produces cytokines such as interleukin-1, TNF-alpha and IL-6." (PMID 27757198, 2016). "Like the pathogenesis of osteoarthritis, macrophages that have infiltrated the synovial membrane produce angiogenic factors like VEGF and inflammatory cytokines like IL-1, IL-6, and COX-2, which further impair the homeostasis of the tendons." (PMID 26556342, 2015). "Both the total and phosphorylated forms of SYK are expressed in increased levels in RA synovial tissues compared with osteoarthritis, and SYK inhibition reduced the expression of IL-6 and MMP-3." (PMID 23249408, 2012). "For instance, TA could reduce the cytokine expression of IL6, IL1β, and TNFα in BV2 microglial cells, human osteoarthritis chondrocytes, in mouse models of ulcers and IL1β in BMDMs." (PMID 40565042, 2025). "Pro-inflammatorycytokines (IL-1β, IL-6, and TNF-α) and anti-inflammatorycytokine (IL-2) levels in mouse models of osteoarthritis were evaluated,resulting in a reduction of serum expression of pro-inflammatory cytokinesand an enhancement of anti-inflammatory activity." (PMID 40300853, 2025). "Several studies suggest that the inflammation induced by interleukin-6 (IL-6) leads to the detachment of articular cartilage through multiple mechanisms, with matrix metalloproteinase (MMP) 13 expression significantly increased in osteoarthritis tissues." (PMID 40500748, 2025). "Genes related to FAI, DDH, and osteoarthritis include COL1A1, MMP13, and IL-6." (PMID 41019141, 2025). "Our findings provide valuable insights into how IL-6 may influence ASC function, highlighting its potential implications for osteoarthritis therapy." (PMID 39768138, 2024).
osteoarthritis (continued). "Furthermore, a substantial decrease was observed in the mRNA expression of inducible nitric oxide synthase, cyclooxygenase-2, 5-lipoxygenase, IL-6, TNF-α and MMP-3 and -13, thereby indicating promising therapeutic implications for osteoarthritis." (PMID 38542192, 2024). "Puerarin, ferroptosis, and osteoarthritis share four targets: PLIN2, PTGS2, VEGFA, and IL6." (PMID 37548663, 2024). "Downregulation of IL-6 and other inflammatory cytokines using the MAP tool in IPA was found to potentially attenuate the function of osteoclasts, osteoblasts, and chondrocytes in osteoarthritis." (PMID 39553645, 2024). "Electroacupuncture in a rat model of knee osteoarthritis led to elevated levels of synovial norepinephrine through β2‐AR, which suppressed excessive IL‐6 production in synovial macrophages by targeting the CXCL1‐CXCR2 pathway, ultimately relieving osteoarthritis." (PMID 39601476, 2024). "Common targets of puerarin, ferroptosis, and osteoarthritis include PLIN2, PTGS2, VEGF, and IL6." (PMID 37548663, 2024). "As for osteoarthritis and DM, the top 5 most related genes were INS, TNF, IL-6, CRP, and IL-1B." (PMID 35719662, 2022). "The increased accumulation of IL-6 at the site of injury most likely leads to increased levels in the circulation: indeed, the level of IL-6 in plasma was over five times in progressive-stage NONFH than in osteoarthritis." (PMID 35573242, 2022). "Recently, increasing studies have uncovered that in diabetic patients with osteoarthritis, diabetic treatment such as DPP-4 could partially improve osteoarthritis symptoms by decreasing the production of inflammatory cytokines such as IL-6, IL-8, and TNF-α." (PMID 35719662, 2022). "Levels of IL-6 in circulation were also elevated in progressive-stage NONFH patients than in osteoarthritis." (PMID 35573242, 2022). "Similarly IL-6 neutralisation blocked HIF2α-induced cartilage destruction and MMP induction in mice, although IL6-/- mice developed more advanced osteoarthritis upon aging." (PMID 35459919, 2022). "The pathogenesis of RA involves many immune cells and cytokines, including interleukin-1 (IL-1), interleukin-6 (IL-6), interleukin-18 (IL-18), and tumor necrosis factor (TNF) as the main pro-inflammatory cytokines, which induce inflammatory response and osteoarthritis injury." (PMID 35833125, 2022). "Levels of IL-6 were nearly five times in progressive stage NONFH plasma than in osteoarthritis, while we did not observe such a difference between end-stage NONFH and osteoarthritis patients." (PMID 35573242, 2022). "DNA hypomethylation was observed in the IL-6 promoter regions in synovial fibroblasts from osteoarthritis patients compared with those from non-diseased study participants." (PMID 34944023, 2021). "Besides, miR-23b restoration promoted the release of proinflammatory factors, including IL-6, IL-8 and TNF-α, and accelerated the apoptosis rate of knee joint chondrocytes, thus promoting the development of degenerative joint disease." (PMID 34046827, 2021). "Additionally, luteolin can effectively reduce proliferation of osteoarthritis cartilage cells, suppress the expression of JNK and p38 in cartilage cells, and inhibit the production of NO, TNF-α, and IL-6." (PMID 33799767, 2021). "In addition, allicin ameliorates the progression of osteoarthritis by decreasing TNF-α, IL-6, and IL-1β in chondrocytes." (PMID 34445305, 2021). "Furthermore, moracin, a flavonoid from Mores alba root bark protects against IL-1β-induced osteoarthritis by reducing inflammatory factors (TNF-α, IL-6, and COX2) via attenuating the NF-κB pathway." (PMID 33371279, 2020). "In addition to chondrocytes, macrophages contribute to inflammation and matrix degradation in osteoarthritis tissues, and inflammatory mediators such as IL-1β, TNF-α, IL-6, PGE2, and NO represent potential targets for osteoarthritis disease modification." (PMID 27411719, 2016).
osteoarthritis (continued). "Increased interleukin 1 beta (IL-1ß), interleukin 6 (IL-6), tumor necrosis factor-alpha (TNF-α) and prostaglandin E2 (PGE2) levels in synovial fluid are seen in internal derangements of TMJ such as anterior disc displacement and osteoarthritis." (PMID 25662545, 2015). "The aim of this work was to compare the expression profile of IL-15Ralpha, its ligand IL-15, TNFalpha and IL-6 and how these cytokines are correlated in SF from RA patients taking as a reference Osteoarthritis (OA), an articular but not autoinmmune disease." (PMID 25879761, 2015). "After resveratrol treatment, no changes in TNFα or IL-8 levels were found, but a significant dose-dependent increase in IL-6 levels was demonstrated in patients with osteoarthritis, but not controls." (PMID 23844973, 2013). "In the osteoarthritis microenvironment, MSCs–Exos exert antigen-specific anti-inflammatory effects by inhibiting T lymphocyte proliferation, reducing the proportion of CD4 and CD8 T cell subsets, and downregulating the expression levels of interleukin 6 (IL-6) and interleukin 1β (IL-1β)." (PMID 39595531, 2024). "These phenomena eventually lead to the deterioration of connective tissues and joints and, ultimately, to osteoarthritis, which results from the presence of various pro-inflammatory cytokines in OA chondrocytes, e.g., interleukin-1β (IL-1β), tumor necrosis factor-α (TNF-α), interleukin-6 (IL-6)." (PMID 39201248, 2024). "In conclusion, l-carnitine augmented the probenecid’s anti-inflammatory effect to attenuate MIA-induced osteoarthritis in rats by provoking the miRNA-373 level and inhibiting the P2X7/NLRP3/NF-κB milieu, leading to the suppression of serum inflammatory cytokines: IL-1β, IL-18, IL-6, and TNF-α." (PMID 37994991, 2024). "However, only IL-6 levels in plasma were higher in patients with progressive-stage NONFH than in osteoarthritis." (PMID 35573242, 2022). "Taken together, the results of this study suggest that modulating expression of IL-33, IL-6, TNF-α, TLRs, DAMPs, and MMPs with vitamin D supplementation may serve as a novel therapeutic to attenuate inflammation and cartilage degeneration in osteoarthritis." (PMID 34842603, 2021). "Previous studies have shown that inhibiting TNF-α in RA reduces local osteoarthritis through a reduction in synovial cell infiltration and the expression of adhesion molecules, chemokines, and cytokines, coinciding with reduced levels of acute phase reactants such as CRP and interleukin (IL)-6." (PMID 34209821, 2021). "Furthermore, increase IL-6 and MMP-13 level have been reported in osteoarthritis." (PMID 32886713, 2020). "The serum PGE2, IL-1β, IL-6, and TNF-α levels were higher in rats with MIA induced osteoarthritis; however, these levels were suppressed in FJH-KO supplemented rats with MIA-induced osteoarthritis compared with those in rats with MIA-induced osteoarthritis (p < 0.05)." (PMID 33233504, 2020). "The improvement in osteoarthritis symptoms in OVX-OA-RAFR decreased the mRNA expression of matrix metallo-proteinase-1 and matrix metalloproteinase-13, tumor necrosis factor-α, and interleukin-1β and interleukin-6 in the articular cartilage compared to OVX-OA rats." (PMID 31262076, 2019). "In addition, the mRNA levels of typical aging markers (e.g., P16 and P21) and inflammation factors (e.g., IL6 and matrix metalloproteinase 13 (MMP13)) that are often upregulated in osteoarthritis were diminished in the articular cavities of the mice with DR8-WT or DR8-mtDRBD." (PMID 31350386, 2019). "We determined the interleukin 6 (IL-6), IL-6 receptor α (IL-6Rα), gp130, receptor activator of nuclear factor κB ligand (RANKL), matrix metalloproteinase 3 (MMP3), TIMP metallopeptidase inhibitor 1 (TIMP1), and Bcl-2 levels in RA and osteoarthritis (OA) serum and synovial fluid." (PMID 29755657, 2018). "Increased circulating levels of IL-6 and IL-10 have been reported in painful osteoarthritis, but this reaction might be absent in the late-disease phase." (PMID 28413731, 2017).
osteoarthritis (continued). "Osteoarthritis is a multi-factorial disease process driven by the master regulators of cellular/ECM destruction, IL-1β and TNFα, pro-inflammatory molecules such as the COX-2-dependent cartilage-destructive enzyme prostaglandin E2 (PGE2), IL-6, IL-8, and the ECM-degrading enzymes such as the MMPs." (PMID 27255741, 2016). "In osteoarthritis synovial fibroblasts, WISP1 can activate αvβ5 integrin, phosphoinositide 3-kinase (PI 3-K), protein kinase B (Akt), and nuclear factor kappa-light-chain-enhancer of activated B cells (NF-κB) pathways that result in the up-regulation of interleukin -6 (IL-6) production." (PMID 26893943, 2016). "Furthermore, the mediators (IL-1β and IL-6) related to arthrosis were not quantitatively higher in fractured knees." (PMID 26037740, 2015). "Given the observed enrichment of IL-6 and IL-1β in local lesions, we measured their levels in the circulation of NONFH and osteoarthritis patients." (PMID 35573242, 2022). "However, the role of visfatin in IL-6 and TNF-α production in osteoarthritis synovial fibroblasts (OASFs) has not been extensively studied." (PMID 29316707, 2018). "Moreover, the treatment with osteotropic factors, such as vitamin D3, IL‐1β, TNF‐α, PGE2, IL‐6, but not PTH, and IL‐17, has been correlated with an increased membranous localization of RANKL on low osteoarthritis osteoblasts compared with high osteoarthritis osteoblasts." (PMID 28425564, 2017).